BRD3 (bromodomain containing 3)
Description:
Chromatin reader that recognizes and binds acetylated histones, thereby controlling gene expression and remodeling chromatin structures. Recruits transcription factors and coactivators to target gene sites, and activates RNA polymerase II machinery for transcriptional elongation. In vitro, binds acetylated lysine residues on the N-terminus of histone H2A, H2B, H3 and H4. Involved in endoderm differentiation via its association with long non-coding RNA (lncRNA) DIGIT: BRD3 undergoes liquid-liquid phase separation upon binding to lncRNA DIGIT, promoting binding to histone H3 acetylated at 'Lys-18' (H3K18ac) to induce endoderm gene expression. Also binds non-histones acetylated proteins, such as GATA1 and GATA2: regulates transcription by promoting the binding of the transcription factor GATA1 to its targets (By similarity).
Synonyms: KIAA0043; RING3L; ORFX; FSHRG2
Tractability: Small molecule: a drug acting on it is in phase 2 or 3 trials; a structure with a bound ligand is known; a high-quality ligand is known; it has a binding pocket of medium quality; it belongs to a druggable protein family. PROTAC: it is named in the literature on targeted protein degradation; UniProt records ubiquitination sites on it; ubiquitination databases record sites on it; its protein half-life has been measured; a small molecule that binds it is known.
Target class: Epigenetic regulator; Bromodomain; Reader
Chemical probes: (+)-JQ1 (high quality), ABBV-744 (high quality), AZD-5153 (high quality), GSK046 (high quality), GSK620 (high quality), GSK789 (high quality), GSK973 (high quality), I-BET151 (high quality), MS436 (high quality), MT1 (high quality), MZ1 (high quality), MZP-54 (high quality), PFI-1 (high quality), Pelabresib anhydrous (high quality), biBET (high quality), bromosporine (high quality), iBET-BD1 (high quality)
Gene: Protein-coding gene on chromosome 9 (134,030,305 to 134,068,555, reverse strand). Ensembl gene ENSG00000169925.
Subcellular location: Nucleus; Chromosome
Subcellular location (Human Protein Atlas): Nucleoplasm
Gene Ontology:
Molecular function: histone H3K18cr reader activity; histone H3K27cr reader activity; histone H3K9cr reader activity; histone H3K9me2/3 reader activity; histone reader activity; lncRNA binding; molecular condensate scaffold activity; protein binding; chromatin binding; protein serine/threonine kinase activity
Biological process: endodermal cell differentiation; positive regulation of transcription by RNA polymerase II; protein localization to chromatin; transcription elongation-coupled chromatin remodeling; regulation of transcription by RNA polymerase II; regulation of DNA-templated transcription
Cellular component: chromatin; chromosome; nucleoplasm; nucleus
Genetic constraint (gnomAD): Loss-of-function variants: 16 observed, 61.37 expected, observed/expected ratio (o/e) 0.26, 90% interval 0.18 to 0.4. The upper end of that interval is the gene's LOEUF score, 0.4, which puts it in group 1 of 6, group 1 being the genes least tolerant of losing a copy. Missense variants: 679 observed, 906.67 expected, observed/expected ratio (o/e) 0.75, 90% interval 0.7 to 0.8. Synonymous variants: 402 observed, 377.36 expected, observed/expected ratio (o/e) 1.07, 90% interval 0.98 to 1.16.
Homologues: Orthologues: chimpanzee BRD3 (99% identical), macaque BRD3 (99% identical), mouse Brd3 (95% identical), guinea pig BRD3 (95% identical), rat Brd3 (95% identical), pig BRD3 (92% identical), dog BRD3 (91% identical), tropical clawed frog brd3 (83% identical), rabbit BRD3 (82% identical), Drosophila melanogaster tbrd-1 (19% identical). Paralogues in human: BRD2 (64% identical), BRD4 (59% identical), BRDT (49% identical), CECR2 (21% identical), BPTF (20% identical), BAZ2B (15% identical), BAZ1B (15% identical), BAZ2A (13% identical), BAZ1A (12% identical), KAT2B (10% identical), KAT2A (9% identical).
Diseases named in the same sentence as BRD3 in open-access papers:
BRD3 is named in the same sentence as 66 diseases in open-access papers, as found by Europe PMC text mining. Sharing a sentence is not in itself a finding about the gene and the disease. The quoted sentences say what the papers report.
nut midline carcinoma (20 papers, 2013 to 2023). A rare, highly aggressive and lethal carcinoma that affects children and young adults. "In NUT carcinoma, which is frequently caused by the fusion of the bromodomains of BRD3 or BRD4, the oncogenic characteristics of BET proteins were initially identified." (PMID 38130463, 2023). "NUT midline carcinoma (NMC) is caused by translocation-derived fusion proteins BRD4-NUT or BRD3-NUT." (PMID 36187481, 2022). "Among NUT carcinoma, BRD4:NUTM1 was the most common variant and only one case harbored BRD3:NUTM1 rearrangement." (PMID 36937407, 2023). "Although the BRD3‐NUT fusion gene has been reported in NUT midline carcinoma, the role of BRD3 in cancers is not well known." (PMID 34605158, 2022). "Gene fusions of nuclear protein in testis (NUT) and BRD4, BRD3, or other genes are a characteristic of NUT carcinoma." (PMID 36077617, 2022). "NUT midline carcinoma (NMC) is caused by a translocation-derived fusion protein, BRD4-NUT or BRD3-NUT, which hyperacetylates the nucleosomal domains including the anti-differentiation genes." (PMID 27827996, 2016). "Interestingly, the pathogenic fusion product of NUT (nuclear protein in testis) with BRD4 or BRD3 (BRD4-NUT or BRD3-NUT) causes NUT midline carcinoma (NMC), which is a rare but poorly differentiated and highly aggressive cancer of the squamous cell lineage that arises in midline structures." (PMID 33879235, 2021). "For example, chromosomal translocation leading to the expression of a fusion between BRD4 (or BRD3) and the nuclear protein in testis (NUT) is causative of a rare cancer form named NUT midline carcinoma (NMC)." (PMID 24497639, 2014). "BI 894999, CCS1477 or the combination of both were administered p.o. daily in three different NUT carcinoma xenograft models, two with BRD4-NUT fusion and one with BRD3-NUT fusion." (PMID 35444289, 2022). "The typical NUT carcinoma harbors BRD4, BRD3, NSD3, or Z4 bromodomain complex (BDC) protein genes as fusion partners to NUTM1 and manifests histologically as an undifferentiated to poorly differentiated carcinoma." (PMID 34997561, 2022). "Of note, the related BET inhibitor I-BET76224 is currently in clinical trials for NUT midline carcinoma, an aggressive epithelial carcinoma characterized by genomic rearrangement of BRD4 or BRD3 (ClinicalTrials.gov identifier: NCT01587703)." (PMID 24220271, 2014). "BET inhibitors are efficacious in models of NUT midline carcinoma (NMC), a rare epithelial tumor type driven by the fusions of NUT protein with either BRD3 or BRD4 genes." (PMID 24293458, 2013). "Nuclear grooves, as found in our case, have been described in one cytology report of a lung BRD3::NUTM1 fusion tumor, but nuclear pseudo-inclusions observed in our case on the cytology specimen have not been reported in NUT carcinomas." (PMID 34997561, 2022). "One study that included 124 patients of NUT carcinoma found that the mOS of nonthoracic primary NUT carcinoma was significantly better than that of thoracic primary NUT carcinomas, and patients with BRD4-NUT fusion had worse mOS than those with BRD3-NUT or NSD3-NUT fusion." (PMID 34660264, 2021).
virus infection (14 papers, 2013 to 2025). "Upon virus infection, BRD3 promotes the recruitment of the IRF3/p300 complex to the promoter of Ifnb1, leading to the transcription and production of type I interferon." (PMID 35743279, 2022). "In the nucleus, formation of the IRF3/p300 complex and p300-mediated acetylation of IRF3 after virus infection is assisted by bromodomain-containing 3 (Brd3)." (PMID 32645843, 2020). "Infection of macrophages with Vesicular stomatitis virus (VSV) downregulated Brd3 expression, which in turn inhibited the ability of macrophages to produce IFNβ, demonstrating that Brd3 can be targeted in viral infections to limit type I IFN responses." (PMID 31052499, 2019). "Here we find that virus infection significantly downregulate Brd3 expression in macrophages and Brd3 knockout inhibits virus-triggered IFN-β production." (PMID 28045112, 2017). "Brd3 interacts with both IRF3 and p300, increases p300-mediated acetylation of IRF3, and enhances the association of IRF3 with p300 upon virus infection." (PMID 28045112, 2017). "The results showed that, after virus infection Brd3 knockout (Brd3-ko) cells showed significantly decreased IFN-β production both in mRNA and protein levels, and, to a much lesser extent, IL-6 production." (PMID 28045112, 2017). "We demonstrated that Brd3 is an indispensable molecule for macrophages to produce IFN-β after virus infection." (PMID 28045112, 2017). "Besides, it has been shown that virus infection in macrophages downregulates BRD3 expression and that BRD3 depletion impairs virus-mediated production of IFN-ß." (PMID 34439792, 2021). "Together with the data mining results of the GEO profiles that reveals Brd3 downregulation after various virus infection (see Results), these evidences strongly suggested that Brd3 may be involved in the process of virus-triggered immune response." (PMID 28045112, 2017). "Collectively, our results raise the possibility that Brd3 expression and regulation has important consequences for Type I interferon responses and targeting Brd3 specifically may have benefits in viral infection." (PMID 28045112, 2017). "Therefore, our work revealed Brd3 as a positive regulator in the production of IFN-β in response to viral infection, and provided new mechanistic insight into the efficient activation of the innate immune response." (PMID 28045112, 2017). "IRF3 could be detected in Brd3 immunoprecipitates and the interaction was increased after virus infection." (PMID 28045112, 2017). "As a positive regulator of IFN-β transcription activation, Brd3 expression was downregulated after virus infection, as demonstrated by genome-wide screening, data mining of the GEO profiles, as well as mRNA and protein level analysis of virus-infected macrophages." (PMID 28045112, 2017). "Virus infection also markedly down regulated Brd3 protein expression in a time-dependent manner." (PMID 28045112, 2017). "We then wondered whether various virus infection would affect the expression of Brd3 in macrophages." (PMID 28045112, 2017). "Therefore, the increased Brd3 interaction with IRF3/p300 complex upon viral infection we detected here might possibly correlated with the acetylation status of either IRF3 or p300 (or both)." (PMID 28045112, 2017). "Currently, accumulating studies have also revealed that the BRD2, BRD3 and BRD4 proteins participate in the host immune response against virus infection." (PMID 32962745, 2020). "As the bromodomains in Brd3 has the ability to recognize acetylated proteins, we then examined the acetylation status of IRF3 after virus infection." (PMID 28045112, 2017). "And the translocation of p65 and IRF3 into the nucleus was not affected either by Brd3 knockout after virus infection or LPS challenge." (PMID 28045112, 2017).
breast cancer (9 papers, 2019 to 2025). A primary or metastatic malignant neoplasm involving the breast. "For example, BRD2 enhances epithelial-mesenchymal transition (EMT) in breast cancer cells, while BRD3 and BRD4 repress EMT." (PMID 37296612, 2023). "Consistent with previous reports, ZBC260 reduced breast cancer cell levels of BRD2, BRD3, and BRD4 proteins in a concentration-dependent manner." (PMID 37968653, 2023). "While BRD2, BRD3, and BRD4 have partially redundant roles at ERα enhancers and gene transcription, a more unique role of BRD3 in ERα+ breast cancer is revealed." (PMID 34540900, 2021). "BRD2, a member of the bromodomain and extra-terminal (BET) family including mammalian BRD3, BRD4 and BRDT, is remarkably over-expressed in breast cancer, gastric cancer (GC), malignant pleural mesothelioma (MPM) and castration-resistant prostate cancer (CRPC)." (PMID 32927435, 2020). "On the other hand, Brd2 and Brd3/4 activate independent transcriptional networks and thereby compete with one another to promote or repress, respectively, the epithelial to mesenchymal transition (EMT) in a breast cancer model." (PMID 34842711, 2021). "Furthermore, when comparing expression levels of BET proteins, we found that BRD2 showed higher expression levels compared to BRD3 and BRD4 in the three cell lines, suggesting that BRD2 could be a major target of (+)-JQ1 in canine mammary cancers." (PMID 31758045, 2019). "ABBV-744 did not significantly alter the levels of BRD2 or BRD3; however, a significant downregulation in BRD4 levels was evident at both 75 nM and 100 nM, indicating the potential selectivity of ABBV-744 towards BRD4 in ER+ breast cancer cells." (PMID 37627092, 2023).
prostate carcinoma (8 papers, 2013 to 2025). A carcinoma that arises from epithelial cells of the prostate gland. "DC50 values for BRD3 levels, of 487 nM and 458 nM, were measured from dosing of prostate cancer cell lines PC3 and 22Rv1." (PMID 39396041, 2024). "While the most consistent and pronounced effects were observed following BRD4 knockdown, loss of BRD2 and BRD3 also inhibited LNCaP cell growth, suggesting that all three BET family proteins contribute to the potent growth responses to BET inhibitors observed in prostate cancer cell lines." (PMID 24293458, 2013). "A strong overlap of the identified eight FAIRE-seq peaks was found with known players in prostate cancer including AR, FOXA1, ERG, bromodomains BRD2 and BRD3 and, interestingly, MYC." (PMID 26412853, 2015). "Indeed, it has been shown that cells expressing prostate cancer-derived SPOP mutants are resistant to BET inhibitor due to elevated expression of BET family proteins BRD2, BRD3, and BRD432,33." (PMID 34599168, 2021). "Besides, SPOP-mutant prostate cancers often accumulate BET proteins, including BRD2, BRD3 and BRD4." (PMID 36357379, 2022). "In another study using the prostate cancer cell line DU145, pretreatment with the BRD3 degrader MZ1 did not affect Smad3 phosphorylation induced by TGF-β." (PMID 40869394, 2025).
leukemia (7 papers, 2014 to 2023). A malignant (clonal) hematologic disorder, involving hematopoietic stem cells and characterized by the presence of primitive or atypical myeloid or lymphoid cells in the bone marrow and the blood. "Notably, Leukemia 1 cells also over-express a number of chromatin regulators, including Brd3 and Polycomb complex members Ezh2 and Suz12, all of which have been linked with leukemia and other cancers." (PMID 25517911, 2014). "Displacement of BRD3/4 by specific inhibitors has already been shown in MLL-fusion positive leukemia." (PMID 26623725, 2016). "The immunological signature enrichment revealed the presence of genes, such as BRD3, PBX2, and WNT5B, involved in HSPC proliferation, self-renewal, and differentiation, found deregulated in leukemia." (PMID 31109375, 2019). "While BRD3/4 inhibition significantly impaired proliferation and survival of MLL-AF9 driven leukemia in both in vitro and in vivo studies, the involved targets did not seem to completely overlap with the MLL-AF9-induced oncogenic program." (PMID 29240787, 2017). "The bromodomain (BRD) and extraterminal (BET) proteins including BRD2, BRD3 and BRD4 have been identified as key targets for leukemia maintenance." (PMID 25989842, 2015).
lung carcinoma (6 papers, 2019 to 2024). "The BRD3 inhibition in lung cancer cell lines has been shown to induce G2/M cell cycle arrest and increased apoptosis rate." (PMID 38303989, 2024). "According to TCGA data, BRD3 expression was higher in lung cancer tissues than it was in tumor‐paired normal tissue." (PMID 34605158, 2022). "Following knockdown of BRD3 with BRD3‐specific siRNA, we found that the growth of lung cancer cells (H1299 and A549) decreased over time." (PMID 34605158, 2022). "Cancer cell encyclopedia data showed that BRD3 mRNA expression levels were elevated in various human cancer cell lines including lung cancer." (PMID 34605158, 2022). "Knockdown of BRD3 with BRD3‐specific siRNA decreased the proliferation and migration of lung cancer cells while also increasing the rate of apoptosis." (PMID 34605158, 2022). "Since BRD3 is highly expressed in lung cancer, we tested whether BRD3 knockdown affected lung cancer cell proliferation." (PMID 34605158, 2022). "In addition, TCGA data showed that BRD3 mRNA expression was significantly higher in lung cancers than the expression in adjacent normal tissues." (PMID 34605158, 2022). "Furthermore, we found that BRD3 silencing increased the apoptosis rate in lung cancer cells compared with the rate observed in the control." (PMID 34605158, 2022). "Additionally, BRD3 mRNA expression was higher in lung cancers than the expression in normal tissues and patients with high BRD3 expression had worse OS." (PMID 34605158, 2022). "Thus, we measured BRD3 mRNA expression in various lung cancer cell lines using RT‐PCR and found that expression was elevated in several cell lines." (PMID 34605158, 2022). "In summary, BRD3 rs2427964C>T may increase BRD3 expression through an increase in promoter activity; this likely leads to poor prognosis for lung cancer patients." (PMID 34605158, 2022). "In additional analysis, BRD3 expression showed a tendency to increase in the rs2427964 T allele in 124 lung cancer tissues, but this trend was not statistically significant (data not shown)." (PMID 34605158, 2022). "Therefore, in a similar manner to BRD4‐targeting inhibitors suppressing NSCLC growth, drugs targeting BRD3 could potentially treat lung cancer." (PMID 34605158, 2022). "USP24 knockdown (KD) in H1299 lung cancer cells and U2OS bone cancer cells decreased levels of the BRD-containing proteins including BRG1, BRD7, BRD1, BRD3, GCN5, PCAF, and TIF1α." (PMID 33257797, 2020). "To determine whether SIN3A is functional in conjunction with BRD3, we conducted an experiment on siRNA‐mediated knockdown of the SIN3A gene in H1299 and A549 lung cancer cell lines." (PMID 34605158, 2022). "Nonetheless, a recent study utilizing a CRISPR screen found BRD2, rather than BRD3 or BRD4, promotes EMT in lung cancer models." (PMID 37461511, 2023).
melanoma (4 papers, 2018 to 2021). A malignant, usually aggressive tumor composed of atypical, neoplastic melanocytes. "Examinations of Human Protein Atlas datasets revealed that overexpression of BET family BRD proteins (i.e., BRD2 and BRD3), BRD9, BRD7, and EZH2 were associated with relatively poor three-year survival in melanoma patients." (PMID 34771678, 2021). "KDM6B, BRD2, and BRD3 were moderately to weakly expressed in melanoma samples, whereas weak staining intensity was observed for BRPF1 and EHMT2 in melanoma samples as compared with normal skin tissue indicating that they are significantly expressed at low levels in melanoma samples." (PMID 34771678, 2021). "JQ1, which targets the BET family of BRD proteins (which includes BRD2, BRD3, and BRD4), effectively inhibited the growth of both the melanoma cell lines even at the lower concentrations." (PMID 34771678, 2021). "The results of immunohistochemistry analyses of melanoma tissues from the Human Protein Atlas indicated that BRD7, BRD9, BRD4, BRD3, and KDM6B were mostly expressed at >75% level." (PMID 34771678, 2021). "BET protein consists of BRDT, BRD2, BRD3, and BRD4, among which BRD4 is mainly involved in melanoma progression." (PMID 33052224, 2020). "Further, silencing of BRD2 or BRD3 did not change the effect of MZ1 on melanoma cell viability compared to control cells." (PMID 33958721, 2021). "Therefore, to mimic the clinical scenario, we conducted a long-term clonogenic survival assay using GSK343 (targeting EZH2), JQ1 (targeting BET family BRD proteins-BRD2 and BRD3), TP-472 (targeting BRD7/9) using multiple BRAF mutant melanoma cell lines (M14, SKMEL-28, A375, and A2058)." (PMID 34771678, 2021).